SMO (smoothened, frizzled class receptor)
Diseases named in the same sentence as SMO in open-access papers (continued):
Sharing a sentence is not in itself a finding about the gene and the disease.
pancreatic cancer (41 papers, 2011 to 2025). "The ablation of the SMO gene in stromal fibroblasts caused increased proliferation of pancreatic tumor cells and the activation of oncogenic protein kinase B (AK1) in fibroblasts." (PMID 32962123, 2020). "Increased SMO expression indicates increased Hedgehog pathway activity in these cells, suggesting evidence for Hedgehog pathway activity in pancreatic cancer–associated stromal cells." (PMID 31744214, 2019). "Inhibition of SMO with GDC-0449 in HCC and colon cancer led to decreased tumorigenesis and SMO knockdown in pancreatic cancer caused a decrease in CSC population as well as the expression of NANOG, a stem cell self-renewal protein." (PMID 38920995, 2024). "Our data are consistent with recent studies in human and mouse models of pancreatic cancer proposing SMO overexpression as a mechanism of activation of this pathway in tumour stroma." (PMID 34831015, 2021). "This 3-gene predictive biomarker (TGFB3, IGF2, and SMO) was found to correlate with tumor growth inhibition in preclinical patient-derived pancreatic cancer xenograft models." (PMID 31338636, 2020). "Immunolabeling of Shh-pathway molecules showed that SMO was localized in the cytoplasm and the cell membrane of pancreatic tumor cells and Gli1 was localized in the cytoplasm and the nucleus." (PMID 31417657, 2019). "For instance, pharmacological inhibition of DYRK1B has been reported to repress GLI expression downstream of SMO and subsequent in vivo tumor growth of both SMOi-sensitive and resistant pancreatic cancer cells." (PMID 31244888, 2019). "For instance, in a model of pancreatic cancer, SMO-independent Gli1 activation promotes transformation and requires both TGF-β and KRAS signaling." (PMID 31244888, 2019). "SMO antagonists were promising drugs for pancreatic cancer in pre-clinical studies; however, clinical trials with SMO antagonists in combination with chemotherapy failed." (PMID 30456390, 2018). "We also suggest that the expression status of SMO in tumors be considered prior to the administration of GDC-0449 as part of a treatment regimen for pancreatic cancer." (PMID 29042665, 2017). "Taken together, these results demonstrate that inhibition of DYRK1B efficiently represses GLI1 expression and reduces the malignant properties of GLI1 dependent cancer cells including pancreatic cancer cells with resistance to SMO inhibitors." (PMID 26784250, 2016). "In pancreatic cancer therapy, combination of a SMO inhibitor, cyclopamine, and gemcitabine, a nucleotide analog, completely abrogate pancreatic cancer metastasis while also significantly reduce the size of the primary tumor." (PMID 27043642, 2016). "Cyclopamine, vismodegib, and other SMO inhibitors have been used widely in clinic for medulloblastoma, ovarian cancer, and pancreatic cancer treatment." (PMID 27043642, 2016). "In pancreatic cancer cells lentiviral-mediated SMO suppression reduced cell proliferation and colony formation in vitro." (PMID 26988232, 2016). "Our previous study and others have reported that the Hh/SMO inhibitor cyclopamine reduces the CD133 expression in pancreatic cancer cells." (PMID 27349387, 2016). "In the present study we show that interfering with DYRK1B dramatically impairs SMO-independent GLI1 expression in RAS mutant pancreatic cancer cells and phenocopies the anti-tumorigenic effect of GLI1 targeting." (PMID 26784250, 2016). "It is important that disappointing results have been reported in the clinical trials of Hh/SMO inhibitors for pancreatic cancer." (PMID 27349387, 2016). "Non-canonical Hh signaling is the result of upregulation of genes involved in the initial steps of the pathway such as SMO upregulation by SDF-1 in pancreatic cancer." (PMID 26988232, 2016). "Another example of combination drug for SMO inhibitors is gemcitabine for the treatment of pancreatic cancer." (PMID 25660620, 2015).
pancreatic cancer (continued). "The activity of SMO inhibitor as a single agent in a pancreatic cancer xenograft model is modest and seems to be mediated by stromal pathway inhibition (Ref." (PMID 25660620, 2015). "Cyclopamine has been explored as an SMO activity suppression agent and to arrest the growth of pancreatic tumors." (PMID 23956768, 2013). "In addition, the immunocytochemical staining in human pancreatic cancer specimens detected a considerable linkage between the expression of both SMO and Gli1 and the hypoxia marker CA9." (PMID 36787054, 2023). "SMO plays an important role in the development of pancreatic cancer cell metastasis." (PMID 32962123, 2020). "The knockdown of SMO could inhibit pancreas cancer cells in terms of self-renewal, epithelial–mesenchymal transition (EMT), invasion, migration, lung metastasis, chemoresistance to gemcitabine and development of pancreatic cancer stem cells." (PMID 32962123, 2020). "PTCH1 directly inhibits smoothened (SMO) and in a mouse model of pancreatic cancer, SMO inhibition may facilitate chemotherapy delivery and extend survival by depleting tumor-associated stromal tissue." (PMID 31817155, 2019). "In addition, pharmacological modulation of the HH pathway in mice revealed accelerated or delayed pancreatic cancer development following SMO inhibitor or HH agonist treatment, respectively." (PMID 27935821, 2017). "HIF-1α stimulates SHH expression in fibroblasts and cardiomyoblasts and SMO in pancreatic cancer, which suggests that, in situ, hypoxia could also induce SHH signaling in WJ-MSC." (PMID 28962669, 2017). "In 2012, Infinity Pharmaceuticals terminated a phase II clinical trial in pancreatic cancer patients employing SMO inhibitor saridegib in combination with gemcitabine as patients treated with this combination had an overall lower survival than the placebo treated group." (PMID 26988232, 2016). "The efficacy of the Hh/SMO signaling inhibitors on pancreatic cancer is still in dispute." (PMID 27349387, 2016). "Preclinical trials explored SMO hedgehog inhibitors, such as cyclopamine, which were able to limit pancreatic cancer metastasis in a spontaneously metastasizing xenograft model and to influence chemoresistance to gemcitabine in pancreatic cancer cells." (PMID 24084722, 2013). "Targeting DYRK1B may therefore overcome the inefficient therapeutic response of pancreatic cancer patients to SMO-inhibitors that target canonical paracrine signaling in the tumor environment rather than non-canonical GLI activity in the epithelial tumor compartment." (PMID 26784250, 2016). "The SMO antagonists including GDC-0449, PF-04449913, etc are presently assessing for pancreatic cancer treatment." (PMID 36865478, 2023). "Gemcitabine-resistant pancreatic cancer cells display a higher expression of SHH, SMO, and GLI1 in comparison with parental cells." (PMID 35154464, 2022). "Thus, the dysregulated SMO in pancreatic cancers could be a therapeutic target." (PMID 32962123, 2020). "This led to a clinical trial of the small molecular SMO inhibitor, IPI-926 (Infinity Pharmaceuticals), and parallel trials of a separate SMO inhibitor, GDC-0449 (vismodegib, Genentech) in patients with pancreatic cancer." (PMID 33198201, 2020). "Hypoxia has been shown to increase HH pathway activation through the upregulation of SHH, Smoothened (SMO), and GLI1 transcription in a ligand-independent manner, leading to enhanced invasiveness of pancreatic cancer." (PMID 32707920, 2020). "Onishi and colleagues confirmed, using triple staining fluorescence immunohistochemistry of surgically-resected pancreatic cancer tissues, that GLI1 and SMO proteins are partially co-expressed with CAIX, a marker of hypoxia." (PMID 32707920, 2020). "The four pancreatic cancer cell lines used in the present study, namely, BxPC-3, Panc-1, MIAPaca-2 (SMO-positive), and SW1990 (SMO-negative), have different SMO expression profiles." (PMID 29042665, 2017).
pancreatic cancer (continued). "There are some SMO antagonists that, such as GDC-0449, IPI-926, XL-139, and PF-04449913, are being evaluated with high hope for treatment of pancreatic cancers." (PMID 23956768, 2013). "Since the blockade of GLI1 does not affect SMO expression, these data indicate that hypoxia facilitates pancreatic cancer cell EMT and invasion through increasing the transcription level of SMO." (PMID 23786654, 2013). "In case of pancreatic cancer, we found the expression of IHH, PTCH1 and SMO in pancreatic cancer cell line, which signified their role of hedgehog pathway activation in this type of cancer formation." (PMID 23935937, 2013). "SMO regulated EMT, invasion and migration of pancreatic cancer stem cells." (PMID 32962123, 2020). "On the other hand, cyclopamine, another SMO inhibitor, failed to induce significant apoptosis in human pancreatic carcinoma cells." (PMID 33312948, 2020). "Multistage development of pancreatic cancer in mouse models is not affected by the deletion of the SMO, which is essential for the transduction of the canonical Hh signal from the extracellular ligand." (PMID 27349387, 2016). "As a result, perturbation of SMO or PTCH1/PTCH2 receptors was not effective to reduce the activation of GLI1/GLI2/GLI3_A in pancreatic cancer model." (PMID 23935937, 2013). "To determine whether SMO or GLI1 is directly regulated by hypoxia, we exposed pancreatic cancer cells to cyclopamine or GLI1 siRNA in the presence of hypoxia." (PMID 23786654, 2013). "From our study we observed the under expressions of various oncoproteins in Hedgehog pathway while perturbing at a time the combinations of the proteins GLI1, GLI2 and SMO in Glioma; SMO, HFU, ULK3 and RAS in Colon cancer; SMO, HFU, ULK3, RAS and ERK12 in Pancreatic cancer." (PMID 23935937, 2013). "However, some clinical trials have been reported that the combination treatment with SMO inhibitor and gemcitabine in patients with pancreatic cancer was not better than gemcitabine alone." (PMID 34237099, 2021). "Since hypoxia simultaneously induces tumor cell EMT, invasion and Hh signaling activation without affecting SHH expression, we hypothesized that hypoxia contributes to increased pancreatic cancer cell EMT and invasion through a SMO-dependent manner Hh signaling." (PMID 23786654, 2013). "Dual blockade of SMO and BRD4 might also contribute to prevent resistance to pan-selective BET inhibitors such as JQ1, because resistance to JQ1 can be mediated by GLI2-dependent upregulation of cMYC and targeting GLI2 restores JQ1 sensitivity in pancreatic cancer." (PMID 33958721, 2021). "Pancreatic cancer cells have been shown to express GLI1 in response to TGFβ and RAS signaling independent of SMO activation." (PMID 26784250, 2016). "According to the report, autocrine SHH-Ptch-SMO signaling is not required for cancer progression and alternative mechanisms keeping the expression of GLI target genes exist in pancreatic cancer cells." (PMID 27349387, 2016). "In addition, we analyzed the role of DYRK1B in the regulation of GLI1 expression in pancreatic cancer and Ewing sarcoma cells, where TGFβ/RAS and the EWS-FLI1 oncogene, respectively, control GLI1 expression independent of canonical SMO activity." (PMID 26784250, 2016). "Furthermore, clinical trials with SMO inhibitors so far have failed to prove a clear therapeutic benefit for patients with non-BCC malignancies including colorectal, ovarian and pancreatic cancer." (PMID 26784250, 2016). "This is because inhibition of SMO by cyclopamine could not reduce vimentin levels, Thus, we speculate that hypoxia enhances EMT and invasion of pancreatic cancer cells through activating a multifaceted factors in which the Hh signaling pathway is a part of an essential network." (PMID 23786654, 2013).
glioma (29 papers, 2013 to 2024). A benign or malignant brain and spinal cord tumor that arises from glial cells (astrocytes, oligodendrocytes, ependymal cells). "Expression of Patched 1 (PTCH1), Smoothened (SMO), and glioma-associated zinc transcription factors (Gli1 and Gli2) were assessed in histological sections using immunohistochemistry and immunofluorescence (IF) techniques." (PMID 29423837, 2018). "In the presence of Hh, the repressive action of PTCH1 on SMO is removed and the downstream pathway is mediated via the glioma-associated zinc transcription factors, Gli1 and Gli2, which translocate to the nucleus and activate Hh-target genes." (PMID 29423837, 2018). "SMO is upregulated in gliomas and is associated with tumour grade and has prognostic implications as well." (PMID 27871300, 2016). "Overexpression of SMO has been described in glioma where it associates with a worse survival." (PMID 27825128, 2016). "First, we transfected two different parental glioma cell lines (L0 and S7) with Flag-tagged SMO, which revealed that SMO localized along the axonemal length of endogenous ARL13B." (PMID 37830570, 2023). "We find that increasing ARL13B in glioma cilia stimulates ciliary elongation and an increase in SMO/GLI2 accumulation." (PMID 37830570, 2023). "We next asked if increasing ARL13B promotes and accelerates a flag-tagged form of SMO to glioma ciliary distal tips." (PMID 37830570, 2023). "In one of our GBM-patient-derived cell lines (L0) expressing Arl13b:GFP transgenes, we observed that glioma cells displayed elongated cilia, accumulation of SMO at their ciliary tips, and excision of their distal tips." (PMID 37830570, 2023). "It is unclear if the accumulated SMO in glioma cilia in ARL13B-overexpressing cells is in an active or inactive state." (PMID 37830570, 2023). "We confirmed that SHH-stimulated ciliary SMO in S7 parental glioma cells was blocked by pretreatment with GDC-0449." (PMID 37830570, 2023). "SMO overexpression was also seen in glioma, and its expression level correlated with tumor grade and patient prognosis." (PMID 33446260, 2021). "Previous study demonstrated that HH signaling activation was present in a subset of GBM tumors, and SMO inhibition was effective in glioma lines highly expressing Gli1, indicating HH signaling is likely to be a driver in a subset of GBMs." (PMID 33446260, 2021). "The present research aimed to investigate the molecular mechanism of circular RNA SMO (circSMO742) in glioma, via targeting miR-338-3p and regulating SMO expression." (PMID 31895689, 2019). "SMO was reported by myriad research as a factor in regulating cancer activities, such as colorectal cancer, glioma, etc.." (PMID 31895689, 2019). "CircSMO742 and miR-338-3p regulated SMO and affected the growth of glioma cells in vitro and in vivo." (PMID 31895689, 2019). "CircSMO742 and SMO were highly expressed in glioma tissues, while miR-338-3p expression was reduced." (PMID 31895689, 2019). "It is noteworthy that our analysis of the TCGA database revealed that higher expression levels of ARL13B and SMO in low-grade glioma correlate with shorter overall patient survival." (PMID 30410731, 2018). "MiR-326 down-regulated the external secretion of TGF-β1 via the SMO/Gli2 pathway instead of by targeting the 3′-UTR of TGF-β1 in the glioma cells, and this resulted in a reversal of the glioblastoma-associated immunosuppressive environment." (PMID 28412740, 2017). "Collectively, these data suggest that increasing functional ARL13B inside glioma cilia may additionally alter the retrograde transport mechanisms, promoting further SMO/GLI accumulation." (PMID 37830570, 2023). "We next examined the effects of increasing ARL13B on glioma cilia morphology and SMO localization." (PMID 37830570, 2023). "Future studies could explore whether glioma cells have or develop a failed positive feedback mechanism leading to ciliary accumulation of SMO." (PMID 37830570, 2023).
glioma (continued). "For example, circSMO742 promotes glioma by sponging miR-338-3p to regulate SMO expression." (PMID 33413401, 2021). "By contrast, despite the widespread use of SMO inhibitors, the value of SMO as a prognostic biomarker is less profound and has only been reported in a handful of cancer types, including bladder cancer, glioma, liver cancer, and head-and-neck cancer." (PMID 34572373, 2021). "The oncogene smoothened (SMO) specific to C2 has been proposed to transduce Hedgehog signaling (SSH) from tumor suppressor patched 1 (PTCH1) to glioma-associated oncogene GLI family zinc finger (GLI) transcription factors and promote glioma tumorigenesis." (PMID 34540693, 2021). "Gliomas with hyperactive SMO initially respond to SMO inhibitors." (PMID 32957513, 2020). "We found SMO could target many circRNAs but only hsa_circ_00001742 (circSMO742) was differently expressed in glioma." (PMID 31895689, 2019). "Thus, the expression of the components of the Shh signaling pathway, including GLI1, GLI2, GLI3, PTCH, and SMO, was found to be common in various tumors of the nervous system, including gliomas, and correlated with a poor prognosis of patient survival." (PMID 30730955, 2019). "CircSMO742 promoted glioma growth by sponging miR-338-3p to regulate SMO expression." (PMID 31895689, 2019). "Even though growth stimulation, Arl13b-mediated SMO upregulation, and F-actin may contribute to glioma ciliary excision, further studies are needed to elucidate the exact mechanisms involved in this process." (PMID 30410731, 2018). "Importantly, the simulative effect of SMO agonist purmorphamine on GLI1 activity in U-87 MG glioma cells was dramatically arrogated by NUSAP1 depletion." (PMID 28899410, 2017). "Additionally, miR-326 inhibited the biological behaviors and stemness of glioma cells by targeting smoothened (SMO)." (PMID 26183397, 2015). "Therefore, in order to suppress the GLI activation in cytoplasm, we directly blocked the activity of GLI1 and GLI2 in cytoplasm and also SMO in membrane of the Glioma scenario (GS) by putting ‘0’ or “OFF” as their logical states." (PMID 23935937, 2013). "Our previous findings implicated a relationship between ARL13B and SMO in glioma cells that may, in part, be independent of SHH." (PMID 37830570, 2023). "Collectively, we may infer from these results that the abnormal expression of circSMO742 caused that only a little miR-338-3p could be free to target SMO mRNA in glioma, so SMO proteins level was higher to promote glioma growth through cells proliferation, migration and invasion." (PMID 31895689, 2019). "Of note, a single miRNA can regulate a multitude of target genes concomitantly; for instance, it has been reported that miR-326 suppresses progression of colorectal cancer by down-regulating nin one binding protein; and miR-326 could repress SMO oncogene in glioma." (PMID 26840018, 2016). "Gliomas with increased ARL13B, SMO, and GLI2 expression are more aggressive, but the relationship to cilia is unclear." (PMID 37830570, 2023). "The Cancer Genome Atlas (TCGA) data sets indicate that gliomas with high ARL13B and SMO mRNA expression correlate with shorter overall patient survival." (PMID 37830570, 2023). "Increasing ARL13B expression promotes the accumulation of both activated SMO and GLI2 in glioma cilia." (PMID 37830570, 2023). "We first examined the relationship of ARL13B expression and another key ciliogenesis gene, IFT88, with the expression of other SHH pathway genes (SMO, GLI2, and SHH) in low-grade glioma (LGG) and high-grade glioblastoma (GBM) using TCGA datasets." (PMID 37830570, 2023). "Thus, we speculated that SMO could competitively bind to circSMO742 with miR-338-3p in glioma." (PMID 31895689, 2019). "Thus, the increase in SMO associated with Arl13b:GFP overexpression in the GBM clones, enrichment which was particularly prevalent in the ciliary tips, may constitute one of the mechanisms stimulating the release of ciliary vesicles in glioma cells." (PMID 30410731, 2018).